INS (insulin)
Diseases named in the same sentence as INS in open-access papers (continued):
Sharing a sentence is not in itself a finding about the gene and the disease.
type 2 diabetes (continued). "GRB14 is a prerequisite for the development of insulin-sensitizing molecules to pathological states as obesity and type 2 diabetes." (PMID 23754948, 2013). "Insulin secretion from pancreatic β-cells plays an essential role in blood glucose homeostasis and type 2 diabetes." (PMID 24109547, 2013). "This study was designed to evaluate the effect of insulin analog initiation therapy on low-density lipoprotein (LDL)/ high-density lipoprotein (HDL) sub-fractions and HDL associated enzymes in type 2 diabetic patients during early phase." (PMID 23617853, 2013). "The results of this pre-planned meta-analysis, utilizing patient-level data, demonstrate that insulin degludec significantly improves health-related quality of life compared with insulin glargine, in patients with Type 2 diabetes starting insulin therapy." (PMID 23199058, 2013). "Regardless of the evidence linking the vascular dysfunction of type II diabetes mellitus with failures in the vascular biology of insulin, there are many reports that attribute these dysfunctions to the very fact of the existing hyperglycaemia." (PMID 23573411, 2013). "In the present study, we examined the efficacy and safety of incretin therapy in patients with insulin-treated type 2 diabetes undergoing HD, using continuous glucose monitoring (CGM)." (PMID 23445717, 2013). "The aim of this study is to compare the efficacy of intensification of insulin treatment with insulin glargine and biphasic human insulin in patients with type 2 diabetes on concomitant therapy with oral antidiabetic drugs (OAD) in daily clinical practice." (PMID 23916120, 2013). "Similar observations have been made in type 2 diabetic patients, where alterations in glucose-stimulated Ca2+ oscillations were closely related to abnormalities in the pattern of insulin secretion." (PMID 23516528, 2013). "A total of 2.7% of insulin‐treated patients with a clinical diagnosis of Type 2 diabetes in the present study were found to have absolute insulin deficiency." (PMID 23659458, 2013). "Insulin-sensitizing and glucose lowering drugs, such as metformin, are used as first-line treatment in the management of type 2 diabetes to improve glycaemic control in patients with insulin resistance." (PMID 23663483, 2013). "Type 2 diabetes is a multifactorial polygenic disease characterised by chronic hyperglycaemia due to impaired insulin secretion and action." (PMID 23879380, 2013). "More studies are needed to examine the nature of sleep disturbances in patients with type 2 diabetes on insulin therapy, particularly among females." (PMID 23383010, 2013). "In type 2 diabetes, the ability of insulin to suppress hepatic glucose production is impaired (referred to hepatic insulin resistance), so the liver produces excessive glucose, contributing to hyperglycemia and glucose intolerance." (PMID 24358267, 2013). "IGF-1 has been shown to increase insulin sensitivity and improve glycemic control in patients with type 2 diabetes." (PMID 23383064, 2013). "Some studies demonstrated that the positive correlation between plasma vaspin concentrations and BMI is more dominant in type 2 diabetes or insulin resistant subjects." (PMID 24367155, 2013). "The PPARγ is a ligand-activated transcription factor involved in lipid metabolism and homeostasis that has been identified as the molecular target of insulin-sensitizing agents used to treat type 2 diabetes." (PMID 23674506, 2013). "People with Type 2 diabetes poorly controlled by basal insulin and oral anti-diabetic drugs (n = 811) were switched to insulin glargine for 6 months, while continuing their oral anti-diabetic drugs." (PMID 22998363, 2013). "TZD drugs are widely used in type II diabetes mellitus to improve insulin sensitivity by inducing the expression of genes involved in adipocyte differentiation, lipid and glucose uptake, and fatty acid storage." (PMID 23476786, 2013).
type 2 diabetes (continued). "Nonetheless, even after 5-week on a high protein, weight maintenance diet subjects with type 2 diabetes had similar overnight fasted plasma insulin concentrations compared with normal protein intake." (PMID 23752495, 2013). "Serum levels of retinol-binding protein-4 (RBP4) correlate inversely with insulin sensitivity in patients with type 2 diabetes." (PMID 23781325, 2013). "The high concentrations of therapeutic insulin required to reduce postprandial blood glucose in patients with diabetes mellitus type II reach 0.5 nM which is sufficiently high also to occupy this hybrid receptor." (PMID 23983688, 2013). "Alterations in insulin signaling and action lead to pathophysiological conditions such as obesity, Type 2 diabetes mellitus (T2DM), and generalized metabolic syndrome." (PMID 23577003, 2013). "A similar series of events is induced in beta cells in high, toxic glucose with a consequent inhibition of insulin synthesis and secretion, leading to beta cell pathology and cell death, a degenerative process resembling that seen in type 2 diabetes (T2DM)." (PMID 24039692, 2013). "Self monitoring of blood glucose (SMBG) has been shown to be as effective in insulin-treated type 1 and type 2 diabetes." (PMID 23876067, 2013). "Fatty liver always accompanies obesity and type 2 diabetes; excessive triacylglycerol accumulation in the liver tissue increases the liver weight and deteriorates hepatic insulin resistance." (PMID 23977216, 2013). "The aim of the present review is to summarize established knowledge and areas for debate with respect to insulin therapy in type 2 diabetes." (PMID 24348585, 2013). "Insulin is used for treatment of both type-1 and type-2 diabetes, and has been one of the most widely prescribed injectable therapeutic polypeptide 20]." (PMID 23483881, 2013). "These rats display increased triglycerides, cholesterol and insulin levels, are mildly hypertensive and eventually develop type 2 diabetes." (PMID 23667622, 2013). "PPARg-agonists are used to treat type 2 diabetes by redistributing adipose tissue from abdominal visceral to subcutaneous compartment, which is thought to be preferable and improve insulin sensitivity." (PMID 23754948, 2013). "Clinically available GLP-1 receptor analogues, such as exenatide and liraglutide, are approved for treatment of type II diabetes since they reduce gastric emptying, glucagon secretion as well as enhance glucose-dependent insulin secretion." (PMID 24204788, 2013). "In insulin resistant and in type 2 diabetic rats, the occurrence of an insulin- and PTH-independent bone anabolic action mediated by GLP-1 has been demonstrated, together with an osteogenic action on altered bone structure on osteoblasts." (PMID 23785355, 2013). "Metformin is worldwide the most prevalently used drug to treat type 2 diabetes and have been utilized in the clinic for more than five decades to improve insulin sensitivity." (PMID 23341947, 2013). "The present study shows that hypomagnesemia occurs in 1 in 5 community-based non-insulin-treated patients with type 2 diabetes." (PMID 24019966, 2013). "This included those with Type 2 diabetes controlled with lifestyle alone or oral hypoglycaemic agents and patients with Type 2 diabetes requiring insulin treatment and patients with stable Type 1 diabetes." (PMID 24358306, 2013). "Global PSQI score was significantly higher in female type 2 diabetes patients with insulin treatment than male (7.52 vs 6.08, P<0.05)." (PMID 23383010, 2013). "Type 2 diabetes or adult onset diabetes is characterized by the inability of insulin to properly metabolize glucose." (PMID 23577036, 2013). "In this aspect, previous studies using ET as a therapeutic approach have described improvements on triglyceride and insulin profiles in fructose overload rats, reduction of inflammatory and oxidant status in type II diabetes, and Obese Zucker rats." (PMID 23777435, 2013).
type 2 diabetes (continued). "All diabetic patients suffered from type 2 diabetes, nine took insulin and 15 took antihypertensive medication." (PMID 24472121, 2013). "The aim of the study was to explore the concept of patient values in the context of making decisions about insulin initiation among people with type 2 diabetes." (PMID 24282518, 2013). "Five observational studies and one intervention study (examining the effects of rye bread on plasma glucose and insulin response) of type 2 diabetes and intermediate biomarkers of type 2 diabetes met the quality criteria (all graded B)." (PMID 24130513, 2013). "Patients with type 2 diabetes (T2D) often experience β-cell failure leading to reduced production and secretion of insulin." (PMID 22776039, 2013). "An elevated muscular expression of FGF-21 was found in patients with type 2 diabetes and insulin was identified as a stimulator of muscle-FGF-21 in two separate studies." (PMID 23533568, 2013). "Type 2 diabetes is a complex metabolic disorder predominantly characterized by defects in insulin secretion in early phase." (PMID 23776622, 2013). "A recent study that followed patients with type 2 diabetes for 10 years reported that the predictors of a decline in eGFR included hypertension, increased HbA1c levels, and insulin use." (PMID 24471138, 2013). "Some similar studies reported that ingestion of foods naturally high in oat or barley beta-glucan improved glycemic and insulin response in overweight or type 2 diabetes subjects." (PMID 24371433, 2013). "This conditioned media was then applied to primary human skeletal myotubes derived from vastus lateralis biopsies taken from patients with type 2 diabetes to examine insulin-stimulated glucose uptake." (PMID 23437184, 2013). "A study has shown that l-arginine treatment (8.3 g/day for 21 days) improved endothelial dilator function and increased insulin sensitivity in patients with type 2 diabetes." (PMID 24133491, 2013). "The changes in whole body glucose levels mediated by PMI5011 correlate with increased insulin sensitivity in primary human skeletal muscle cells and in rodent models of type 2 diabetes." (PMID 23437325, 2013). "Pio, a member of the thiazolidinedione drug class, is used in the treatment of patients with type 2 diabetes to increase tissue sensitivity to insulin." (PMID 23762423, 2013). "Dapagliflozin, a potent and selective SGLT2 inhibitor, has been shown to improve glycemic control in patients with type 2 diabetes when used as monotherapy or in combination with metformin, sulfonylureas, thiazolidinedione, or insulin." (PMID 23425012, 2013). "The aim of this pre-planned meta-analysis was to compare the effect of insulin degludec and insulin glargine on health-related quality of life in patients with Type 2 diabetes starting on basal insulin, in combination with oral anti-diabetic drugs." (PMID 23199058, 2013). "Approved for the treatment of type 2 diabetes, PPARγ agonists can improve glucose disorders mainly through insulin-sensitizing effects in muscle and adipose tissue." (PMID 23424659, 2013). "Type 2 diabetes is a multifactorial disease defined by a high plasma glucose level and is characterized by both insulin resistance and impaired insulin secretion by pancreatic β-cells." (PMID 25379289, 2013). "A large number of studies have provided evidence for the pivotal role of oxidative stress in insulin resistant states such as obesity, the metabolic syndrome and type 2 diabetes." (PMID 24177571, 2013). "A major defect behind type 2 diabetes is inadequate insulin secretion, that would be needed to compensate for decreased insulin sensitivity." (PMID 24319481, 2013). "Based on our findings more research will be performed towards elucidating the exact mechanism of action of GO2KA1 for type 2 diabetes prevention, with focus on the potential insulin sensitizing effect on muscle and fat cells." (PMID 23839092, 2013).
type 2 diabetes (continued). "Impaired glucose and insulin metabolism lie along the etiologic trajectory that results in type 2 diabetes." (PMID 24322525, 2013). "Future research should evaluate the potential effects of olive leaf polyphenols on insulin sensitivity and glycaemic control (HbA1c) in patients with type 2 diabetes, and compare any such effects to conventional therapy (e.g. metformin)." (PMID 23516412, 2013). "As antagonists of insulin action, glucocorticoids are major sources of increased glucose production in type 2 diabetes though upregulation of key enzymes in gluconeogenesis." (PMID 23819126, 2013). "Studies have shown some cancer survival benefit in type 2 diabetes patients treated with the biguanide and metformin compared to those treated with insulin or sulphonylureas (stimulate insulin secretion from pancreatic β-cells)." (PMID 23573093, 2013). "Molecular and cellular studies have demonstrated that the mineral zinc plays a key role in the synthesis and action of insulin under normal physiological conditions and in type 2 diabetes (T2D)." (PMID 24093747, 2013). "Several studies have demonstrated the clinical potential of a stepwise intensification of prandial insulin, building on an existing basal insulin regimen, for the management of Type 2 diabetes." (PMID 22998363, 2013). "The role in glucose regulation through insulin secretion suggests a therapeutic potential for GIPr agonism in type 2 diabetes." (PMID 23689510, 2013). "It has been reported that in obese and type 2 diabetics there is an inverse relationship between insulin sensitivity and the percent of myosin heavy chain IIx (MYH1)." (PMID 23805253, 2013). "TZDs including TRO were once widely used to treat type 2 diabetic patients since they were found to increase insulin sensitivity in peripheral tissues." (PMID 23424659, 2013). "The strength of this study is the identification of a potential novel role for SPARC in the regulation of insulin secretion relevant for the onset of Type 2 diabetes." (PMID 23840838, 2013). "More specifically, less than one third of individuals with type 2 diabetes using OADs, either alone or in combination with insulin or GLP-1 receptor agonists, achieved glycemic control as defined by HbA1c <7.0%." (PMID 23800082, 2013). "By contrast, only a few studies have examined the role of these RNAs in insulin secretion and type 2 diabetes." (PMID 24109547, 2013). "In this study, we investigated the mechanism of insulin sensitization of insulin therapy by examining the anti-angiogenic factor PEDF in type 2 diabetic patients." (PMID 24367624, 2013). "Meanwhile, low dose of STZ has known to induce mild defect in insulin secretion, which is similar to the characteristics of the later stage of type 2 diabetes." (PMID 23762147, 2013). "Induction of type 2 diabetes significantly increased serum glucose and insulin levels as well as HOMA-IR in untreated type 2 DM group compared to the non-diabetic group." (PMID 24555069, 2013). "Effect of DYSGT in type II diabetes is similar to rosiglitazone which is ameliorated in insulin sensitivity." (PMID 24062791, 2013). "Here, we strongly repudiate misconceptions, resulting from observations that melatonin reduces the plasma insulin level, that the blockage of melatonin receptors would be of benefit in the treatment of type 2 diabetes." (PMID 23535335, 2013). "In a relatively early stage of type 2 diabetes, insulin secretion is increased and melatonin is decreased—a pattern that is observed in rats and humans." (PMID 23535335, 2013). "Alteration of this localization can indirectly affect insulin responsiveness of GLUT4, impairing glucose transport and possibly contributing to the development of insulin insensitivity and type 2 diabetes." (PMID 23665900, 2013). "Dissecting the mechanisms that contribute to insufficient insulin secretion in type 2 diabetes patients is an important goal of understanding the disease." (PMID 23879380, 2013).
type 2 diabetes (continued). "To date, there is only one peer-reviewed human clinical trial that monitored the effect of resveratrol on insulin sensitivity in type II diabetes." (PMID 23607096, 2013). "The aim of this study was to determine the short term effect of insulin analog initiation therapy on LDL/HDL sub-fractions and HDL associated enzymes in type 2 diabetic patients." (PMID 23617853, 2013). "This meta-analysis demonstrates that treatment with insulin degludec leads to an improvement in health-related quality of life compared with insulin glargine in patients with Type 2 diabetes starting on insulin therapy." (PMID 23199058, 2013). "Testosterone replacement therapy (TRT) in hypogonadal men with type 2 diabetes and/or metabolic syndrome improves insulin sensitivity in the short-term." (PMID 24069277, 2013). "IR is typically defined as a condition of diminished ability of target tissues to take up and metabolize glucose in response to insulin, and it plays a major role in the development of type 2 diabetes." (PMID 23326550, 2013). "The same resistance phenomenon takes place in type-2 diabetics who, although they produce large amounts of insulin, are still hyperglycemic and thus insulin-resistant." (PMID 24071981, 2013). "Usage of an insulin secretagogue can selectively enhance early meal-induced insulin secretion, resulting in improved postprandial hyperglycaemia, thus preventing type 2 diabetes." (PMID 23691521, 2013). "In clinical studies, it has been reported that the levels of plasma apelin were elevated in insulin-resistant subjects and in morbidly obese individuals with type 2 diabetes, compared with normal controls." (PMID 23437347, 2013). "The objective of our study was to explore the perceived value and practice of SMBG among South Asian and Black Caribbean individuals with non-insulin-treated type 2 diabetes using the Health Belief Model." (PMID 24119213, 2013). "Type 2 diabetes, which was previously called adult-onset diabetes, can be controlled with diet and exercise, and with drugs that help the pancreas make more insulin or that make cells more sensitive to insulin." (PMID 23843750, 2013). "In conclusion, the present study provides evidence that EE ameliorates type 2 diabetes by enhancing glucose uptake, improving insulin resistance and pancreatic islet cell function, and regulating glucose metabolism." (PMID 23690865, 2013). "Nevertheless, SOLVE is the largest study of insulin initiation in real-life clinical practice, and otherwise broad inclusion criteria and the focus on insulin initiation in type 2 diabetes are important study strengths." (PMID 24499517, 2013). "Synthetic agonists of PPARγ include the thiazolidinedione (TZD) class of drugs, which are widely used to improve insulin sensitivity in type II diabetes." (PMID 23476786, 2013). "In which we found that the serum PEDF was reduced by the insulin therapy in type 2 diabetic patients." (PMID 24367624, 2013). "In an elderly man suffering from type 2 diabetes and psoriasis treated with etanercept, insulin was gradually reduced and finally replaced with rosiglitazone and repaglinide for frequent episodes of hypoglycaemia occurred." (PMID 24124913, 2013). "Of the various forms, type 2 diabetes is the most common and is characterized by inadequate insulin secretion." (PMID 23516528, 2013). "Type I diabetes mellitus refers to the juvenile offset stage when the pancreas cannot produce sufficient insulin, while type II diabetes mellitus reflects the inability of the body to use the secreted insulin." (PMID 26824930, 2013). "In a previous study, exercise interventions improved the insulin sensitivity of patients afflicted with lifestyle-related diseases such as type 2 diabetes and hypertension." (PMID 24453904, 2013). "The low dose of STZ injected to the insulin resistant rats produced frank hyperglycemia which mimics human type 2 diabetes." (PMID 23606892, 2013).